MX1 (MX dynamin like GTPase 1)
Diseases named in the same sentence as MX1 in open-access papers (continued):
Sharing a sentence is not in itself a finding about the gene and the disease.
infection (continued). "Despite inter-individual variability and cohort heterogeneity, our findings regarding four DMPs (IFI44L, MX1, DDX60, and RABGAP1L) and two DMRs (PARP9 and GNA12) replicate changes described both in the acute phase of infection and at long-term follow-up." (PMID 42288901, 2026). "Total RNA was extracted 4 and 8 h post-infection, after which the relative levels of IFNβ, OAS1, MX1, and MX2 RNAs were determined by quantitative real-time PCR (qRT-PCR)." (PMID 41585476, 2026). "Transcriptome analysis of this study showed that untreated infection induces a strong ISG signature, including IFIT1–IFIT3, OASL, RSAD2, and MX1, consistent with canonical antiviral programs." (PMID 41480150, 2025). "At h 36, the infection with SIV H1N1 (MOI 0.01) induced increases of approximately 20-, 70-, 30-, and 5-fold in IFN-β, Mx1, Mx2, and IFITM1, respectively, while these changes were 90-, 250-, 300-, and 25-fold for SIV H3N2 (MOI 0.01)." (PMID 40565228, 2025). "For this purpose, PBE cells were challenged with SIV H1N1 or H3N2 and the expression of IFN-β and the antiviral factors Mx1, Mx2, IFITM1, OAS1, OAS2, and OASL were evaluated at different hours post-infection." (PMID 40565228, 2025). "Consistently, ASFV-WT infection markedly dampened the mRNA levels of ISG54, ISG56, ISG15, and MX1, which are spurred by IFN-β in PAMs." (PMID 40618140, 2025). "In challenge studies, Mx1-expressing mice are protected from a lethal dose of HPAI virus, whereas Mx1-negative mice succumb to infection." (PMID 40586559, 2025). "Given that LD accumulation is required for interferon response in the early infection of virus, we measured two ISGs, ISG15 and MX1, which can be induced by type I interferon and possess antiviral capacities." (PMID 39891192, 2025). "Some other infection-responsive genes like IFI144, MX1, MX2, IFIT3, and HLA-DOA were also observed proximal to those altered ERVs, and showed positive co-expressions with their proximal ERVs, wherever they located." (PMID 40176799, 2025). "A subtly reduced Mx1 and ISG15 induction was seen after infection with BAD-ΔUS2,3,6,11 and BAD-ΔUS2,3,6." (PMID 40143353, 2025). "Upon infection, this configuration drives robust activation of type I interferon signaling via IRF3, upregulation of key interferon-stimulated genes (ISGs; Mx1, Rsad2), and concurrent suppression of virus-required metabolic pathways (P450, ACSF)." (PMID 41574307, 2025). "Differential gene expression analysis in hROs at 24 h post-infection revealed a robust upregulation of antiviral genes (e.g. IFIT1, IFIT2, MX1, and OAS2) and pathways related to antiviral innate immunity and viral replication in rRVFV versus mock comparisons." (PMID 41255708, 2025). "In contrast, in the case of attenuated NH/P68, the fold-changes values of MX1, OAS2 increased slightly as infection progressed." (PMID 40530033, 2025). "In this study, despite significant production of IFNs in the lung during the infection, ISG15, ISG12(A), MX1, and MX2 genes were downregulated at 14 dpi, suggesting that PRRSV employs strategies to inhibit ISGs and facilitate in vivo replication." (PMID 40459260, 2025). "Of note, the cultures cluster derived from XX T21-12 specimen, which had lowest infection level, has consistently the highest STAT1 and STAT2 expression, corresponding to the highest MX1 expression." (PMID 40445428, 2025). "The study of the expression of IFNs, antiviral factors, cytokines and chemokines after 6 and 24 h pots-infection with PRRSV showed significant increases in IFN-β, IFN-γ, Mx1, and OAS1 only at h 24 after the viral challenge, compared to non-infected pAMs." (PMID 41155369, 2025). "The observed upregulation of Mx1, Ifi44, and Sting1 is indicative of type I interferon (IFN-I) pathway activation, often triggered by cellular stress, infection, or cytosolic self-derived mitochondrial DNA (mtDNA)." (PMID 41465333, 2025).
infection (continued). "Similar results were observed with the virulent strain used in our study (26544/OG10), where expression levels for some key antiviral genes (DDX58, DHX58, IFIH1, MX1, and OAS2) decreased slightly as infection progressed." (PMID 40530033, 2025). "RT-qPCR analysis of RNA isolated from hGBOs at 48 h post-infection revealed a robust upregulation of IFNB1 and IFNB1-stimulated IFIT1, MX1, CXCL10, and OAS1." (PMID 41255708, 2025). "LFBK cells stimulated with transfected poly(dA:dT) (10 μg/mL) to detect IFN-β, IFN-α, IRF7, IRF3, PKR, MX1, ISG56, and ISG15 at 2, 24, and 48 h infection times using qRT-PCR was investigated." (PMID 40500801, 2025). "Analysis of transferred cells 5 days after infection demonstrated an increased frequency of pTCM cells expressing CD62L and intermediate for CXCR5 expression amongst transferred Mx1(GFP)+ cells." (PMID 39321257, 2024). "Consistently, knockdown of PCGF3 increased the expression levels of ISGs (ISG15, IFIT1, OAS2, MX1 and IRF7) and IFNB1, and decreased the VSV replicates (RNA level and virus titer) after VSV infection." (PMID 39368978, 2024). "As shown in, we observed that knockdown or overexpression of MDA5 can significantly inhibit or promote the expression levels of IFN-1, Mx1, ISG15, and Viperin upon SCRV infection or poly(I:C)-HMW stimulation." (PMID 39347580, 2024). "Only five DEPs were common for both infections in both upper and lower trachea, including four interferon stimulated proteins (OASL, MX1, IFIT3, and ISG15) and the GTPase, DRG2." (PMID 39247193, 2024). "Overexpression confirmed cytoplasmic expression of fMx1 as well as its ability to inhibit infection and replication of IAV, noting that this antiviral effect of fMx1was modest when compared to cells overexpressing either human MxA or mouse Mx1." (PMID 38866913, 2024). "Four important antiviral ISGs, MX1, MX2, ISG15, and IFI6, were found to be upregulated after infection with either strains of IAV in the lower trachea." (PMID 39247193, 2024). "There was a minimal induction of type I IFN (IFN-β) and MX1, a canonical ISG highly induced by both type I and III IFNs, at 24 h post-infection." (PMID 38675974, 2024). "The 17 DEGs upregulated after infection with huH1N1 were shared with the swH1N1 infection (DDX58 (RIG-I), RSAD2 (Viperin), MX2, MX1, OAS1, ANGPTL4, IRF7, ISG15, IFIT1, ISG12(A), DDX60, BST2, IFI44, XAF1, LGALS3BP, RTP4, and IFI6)." (PMID 39247193, 2024). "Nonetheless, for nose samples which did yield RNA sequencing data, we found clear evidence of MX1 and IFI27 responses in participants who developed a replicative infection." (PMID 39616162, 2024). "In contrast, while viperin was also highly induced at 72 h post-infection with IPNV31.75 (3.1-logfold increase), mx1 only displayed a weak but still significant induction at the same timepoint with this virus (0.5-logfold increase)." (PMID 38951796, 2024). "Two mRNAs were down-regulated in all treatment groups at the later time points post-infection, namely, CNTNAP1 and NR4A1, while twenty mRNAs were up-regulated in all later time point treatment groups, including IFI6, LY6E, MX1, OASL, STAT1, and CMPK2." (PMID 38675946, 2024). "Although ncp BVDV infection leads to the inhibition of Mx1 expression in vitro in cell culture, calves infected with ncp BVDV showed strong Mx1 expression." (PMID 39224597, 2024). "We identified important genes DE in both our in vitro and in vivo infection models consistent with previous studies, namely, TLR3, IFIH1 (MDA5), SOCS1, OASL, DDX60, STAT1, MX1, CMPK2, LY96 (MD-2), STAT1, STAT2, TRIM25, IRF7, and IFIT5." (PMID 38675946, 2024). "The results indicate that LGP2 knockdown (siRNA si-2 shows the best inhibition effect was chosen) significantly increases the mRNA levels of IFNβ, ISG56, Mx1 and IL6 at multiple post infection time points, and IκBα and CXCL10 at 24 hpi." (PMID 37656756, 2023).
infection (continued). "The results are consistent with the downregulation of IFN-β induced by the virus; aMPV/C infection significantly reduced poly (I·C)-induced OASL and MX1 mRNA." (PMID 36537793, 2023). "As newborn piglets were infected with the porcine epidemic diarrhea virus, the expression of both antiviral genes MX1 and MX2 were highly significantly upregulated and peaked at 24 h post-infection, resulting in an intense inflammatory response." (PMID 37628612, 2023). "Many antiviral ISGs were upregulated in early stages of infection, with IFI27, OTOF, ISG15, MX1 and USP18 the most highly overexpressed." (PMID 37077524, 2023). "Deletion of ORF8 increased the early expression of MX1 and ISG15 at 1 dpi in the lungs of mice and IFNβ in human organoids at 24 hpi, suggesting that ORF8 is an IFN antagonist at early times post-infection." (PMID 37623322, 2023). "Along with STAT1, MX1 and ISG15 were upregulated in the present study, similar to HUVEC cells after infection by Rickettsia conorii bacterium." (PMID 37384298, 2023). "Western blotting confirmed that p38β knockdown led to an increase in MX1, a prototypical ISG, and specifically in the context of infection." (PMID 37345956, 2023). "Both, infection with virus and treatment with pan-IFN, strongly induced MX1 expression in the rhesus macaque kidney cell lines." (PMID 37146034, 2023). "As expected, we observed a 3-fold increase in MX1 promoter activity in both RTG2 and RTgill cells with VHSV Ia infection alone." (PMID 36851680, 2023). "Bulk RNA sequencing of suspension organoids at 3, 7, 10, and 14 days post-infection revealed up to 26-fold time dependent promotion of interferon-stimulated genes such as IFIT3, MX1 and MX2, consistent with an innate antiviral response." (PMID 37205380, 2023). "Deletion of ORF6 significantly increased induction of IFN-stimulated genes MX1 and ISG56, indicating that ORF6 was an antagonist of IFN-I signaling in the context of infection." (PMID 37197199, 2023). "Knockdown of circMORC3 can significantly promote the expression levels of ISG15, Mx1 and Viperin upon SCRV infection." (PMID 38150467, 2023). "qRT-PCR assay showed that eight antiviral-related mRNA including IRF3, IRF7, IKKβ, TBK1, IFIT1, IFI44, MX1 and ISG15 displayed significantly stronger and quicker response at early infection under 20 °C." (PMID 37627029, 2023). "Vaccination with Nsp1-K164A/H165A or infection with WA1/2020 blocked NP deposition and MX1 upregulation in the Delta- and BA.1-challenged groups." (PMID 37296125, 2023). "The relative mRNA expression levels of Mx1 and TOP1 were significantly upregulated, whereas those of eIF4E, G6PD and PGAM1 were significantly downregulated in PK-15 cells during infection with SVA." (PMID 35632606, 2022). "Compared with the cells transduced with control shRNA, PRV-induced transcription of Ifnb1, Mx1, and Isg56 was increased in UL13-knockdown cells in different periods post-infection, suggesting that knockdown of UL13 enhances PRV-triggered antiviral responses." (PMID 35584187, 2022). "The results showed that infection of these ZIKV strains also induced mRNA and protein expression of TRIM22, which is consistent with other ISGs, such as MX1, IDO1 and RSAD2." (PMID 36042495, 2022). "Results showed that MX1, MX2 and OAS1 were over-expressed in SARS-CoV-2-infected A549 cells (p < 0.01 for MX1, ISG15, and OAS1; and p < 0.05 for MX2), and Calu-3 cells (p < 0.05 for MX1, ISG15, and OAS1; and p < 0.01 for MX2) compared with mock infection." (PMID 36298734, 2022). "Others, such as interferon-induced GTP-binding protein MX1, importin subunit alpha-5 KPNA1, and members of the HNRNP complex, were upregulated after infection." (PMID 36298696, 2022). "Inconsistent with the observed trend in the IFNB1 level, persistent upregulation of numerous ISGs, including CXCL10, MX1, and ISG15, was observed in response to SARS-CoV-2 infection from 3 to 7 days post-infection." (PMID 34104087, 2021).
infection (continued). "To accomplish this, we first exposed SC to ZIKV for 1 h and then measured ZIKV envelope (E) and MX1 protein levels by immunofluorescence assay (IFA) and ZIKV infectious progeny in the supernatant by plaque assay each day for up to 5 days post-infection." (PMID 34079533, 2021). "In the presence of HO infection, the stimulatory effect of IFNT on expression of GBP4, ISG15, HERC5, RSAD2, IFIH1, IFIT3, and MX1 was significantly reduced (IFNT vs. IFNT+HO, P < 0.05–0.01)." (PMID 33898551, 2021). "Some interferon stimulated genes such as OAS1, OAS3, MX1, and RSAD2 that were strongly induced by rDEN2Δ30 infection are also known to be regulated in natural infection." (PMID 34031380, 2021). "In adult Xenopus, FV3 infection also induces a rapid response (as early as 1dpi) of type I IFN and Mx1 and 2, as well as pro-inflammatory and inflammatory-related genes (IFNγ, IL-1β, and TNF-α) in the kidney." (PMID 34675918, 2021). "The impact of siMX1 and siIFIT1 was further evaluated by measuring ZIKV genome copies at 48 and 96 h post-infection and confirmed that MX1 and IFIT1 silencing only affected ZIKV RNA replication at the later time point of infection." (PMID 34079533, 2021). "Subsequent experiments also revealed that the corresponding increase in MX1 and IFN-β levels was inversely related to ZIKV propagation in SC, and that the priming of IFN-I response in SC prior to infection significantly hindered ZIKV replication." (PMID 34079533, 2021). "In our study, the expression of IFN-α in the spleen and the expression of antiviral proteins (OASL, MX1, and IFITM3) in the spleen and kidney were increased after GNAstrV infection." (PMID 33647718, 2021). "Macrophages and NK cells are critical innate cell effectors in Xenopus host response during early stages of FV3 infection, and increased expression of IL-1β, TNF-α, Mx1, and IFN-γ genes was detected in infected tissues and leukocytes of adult frogs." (PMID 34675918, 2021). "Transcriptome analysis of the nasal turbinates and lungs indicated that female ferrets had significant increases in interferon response genes (OASL, MX1, ISG15, etc.)on day 2 post infection which was delayed in aged males." (PMID 33469587, 2021). "To investigate, SC were pretreated with 5 pg/mL (1 IU/mL) of recombinant human IFN-β for 24 h prior to infection (MOI 1) and ZIKV replication as well as MX1 and IFIT1 expression were then evaluated by RT-qPCR at 48 h post-infection." (PMID 34079533, 2021). "ISGs and immune response genes such as IFIT1, IFIT2, IFIH1, MX1, MX2, and RSAD2 were highly down-regulated in response to all viruses at later time points of infection, confirming our transcriptome data." (PMID 33791243, 2021). "Significant inhibition of Mx1 expression was seen through the course of anti-IFNAR Ab treatment (days −1 through 2), with recovery of IFNAR signaling on day 4 after PVM infection." (PMID 34160242, 2021). "Following transfection with specific siRNAs against IFIT1 or Mx1 (siIFIT1, siMx1) and subsequent infection with HCMV for 48 h, we achieved a ~60% reduction in IFIT1 protein expression and near to complete silencing of Mx1 protein." (PMID 34162877, 2021). "Although a majority of SC expressed MX1 by 120 h post-infection, we found that SC that were positive for ZIKV-E exhibited low levels of MX1 in comparison to the strong signal observed in neighboring uninfected cells." (PMID 34079533, 2021). "Several restriction factors (IRF1, MX1, STAT1, C18orf25) known to limit lytic infection were expressed at lower levels in the lytic subcluster." (PMID 33914843, 2021). "Then, knockdown or overexpression NARL also can significantly inhibit or promote the expression levels of TNF-α, MX1, and ISG15 upon SCRV infection." (PMID 33581111, 2021). "This resulted in significant silencing of MX1 and IFIT1 at 48 h post-infection (72 h post-transfection) that remained up to 96 h post-infection." (PMID 34079533, 2021).
infection (continued). "The MxA insensitivity of JOSV was further analyzed in vivo, using experimental infections of C57BL/6 mice that express the entire human MX1 gene locus as a transgene (hMX1-tg)." (PMID 33196685, 2020). "Importantly, PEAV significantly inhibited mRNA expression of IFN-α, IFN-β, OAS, Mx1, and PKR, the genes involved in modulation of the host immune responses, in infected Peyer's patches, indicating that PEAV can overcome the antiviral response to cause damage when infection occurs." (PMID 32719818, 2020). "Because both ISG15 and USP18 regulate the type I IFN signaling pathway, we evaluated Mx1 (another ISG) expression in ISG15-knockdown cells and USP18-knockdown cells following IFN-α pretreatment and subsequent infection with CSFV." (PMID 32093773, 2020). "Innate antiviral defense genes, namely ISGs (e.g., MX1, OAS1, STAT1, STAT2, ISG15), are upregulated early in fatal infection and their expression increases dramatically throughout infection indicative of dysregulated innate immune response." (PMID 32992829, 2020). "Upon fetal infection, a set of core responsive IFN-inducible genes (CXCL10, IFIH1, IFIT1, IFIT3, ISG15, and MX1) were strongly upregulated in both tissues." (PMID 33148169, 2020). "Interestingly, MDA-5 (for melanoma differentiation-associated gene 5), MX1 (for myxovirus resistance 1), OAS1 (for oligoadenylate synthetase 1), ISG20 (for Interferon Stimulated Exonuclease Gene 20) and RIG-1 (for reticnoic acide-inducible gene 1) were up-regulated at day 5 after infection." (PMID 33490061, 2020). "To confirm these results, we used real-time quantitative PCR (qPCR) to analyse mRNA levels of the “classical ISGs” Mx1, IFI6 and IFIT5 upon infection with the knockout viruses." (PMID 33352813, 2020). "To understand the antiviral response in the CHME3 human microglial cell line, we next investigated the expression levels of antiviral genes MDA5, RIG-I, MX1, IRF7, IFNβ, and ISG15 following infection with PRVABC59 ZIKV." (PMID 32373079, 2020). "We found that the mRNA expression levels of ZAP, MX2, MX1, PKR, OASL, and ISG15 were significantly higher in the Lp-1s treated group than in the TGEV infected group at various points after infection." (PMID 31781061, 2019). "In ducks that have a strong IFN-β response on the first day post-infection with HPAI H5N1 viruses, Mx1 mRNA is highly upregulated 1–3 dpi, in lung, spleen and brain tissues." (PMID 30634569, 2019). "SCs responded to infection with increased expression of mRNAs for IFNβ, IFNλ, IFIT-1, Mx1, NLRP3, IL-23A, IL-6 and TNFα." (PMID 31289325, 2019). "Total cellular RNA was extracted at 3, 6, 9, 12, 24, 48, and 72 h after infection, and the abundance of HCV RNA and mRNA levels of the ISGs MX1, SOCS3, IFNβ, and OAS2 were quantified by qRT-PCR." (PMID 31138826, 2019). "For example, many well-known interferon-induced antiviral defense proteins (e.g., MX1, several IFIT proteins, several oligoadenylate synthase proteins) were relatively strongly produced at late stages of infection." (PMID 31797923, 2019). "We demonstrate that induction of genes such as Oas, Mx1, Ifit reported to be regulated by type I IFN signaling, is totally dependent on IFN-γ signaling during infection with T. gondii." (PMID 31253760, 2019). "As representatives of antiviral ISGs, protein kinase R (PLR; encoded by EIF2AK2), Viperin (encoded by RSAD2) and MX dynamin-like GTPase 1 (MX1) are widely known, and these ISGs strongly inhibit the infection of a broad range of viruses." (PMID 30915053, 2019). "Although there were differences in induction of some ISGs (IFITM3, IRF3, ISG15, VIG1, and MX1), mRNA levels of type I IFNs were below the detection limit in pLNs or similar in spleens of B6 and CD169−/− mice post-FVC infection." (PMID 30595553, 2019).